VIM (vimentin)
Diseases named in the same sentence as VIM in open-access papers (continued):
Sharing a sentence is not in itself a finding about the gene and the disease.
pulmonary hypertension (3 papers, 2022 to 2025). Increased pressure within the pulmonary circulation due to lung or heart disorder. "A number of very interesting works have been devoted to vimentin involvement in vascular diseases, including pulmonary arterial hypertension." (PMID 35453578, 2022). "It was especially shown that vimentin phosphorylation is one of the main stages of endothelial-to-mesenchymal transition in pulmonary hypertension." (PMID 35453578, 2022). "Myofibroblasts are considered to responsible for the production of ECM during fibrosis, as specific markers of myofibroblasts, our experimental results demonstrated that both α-SMA and vimentin protein expression levels were markedly elevated in the MCT-induced pulmonary hypertension group." (PMID 40346622, 2025).
rectal cancer (3 papers, 2020 to 2024). A primary or metastatic malignant neoplasm that affects the rectum. "Cancer stem cell (CSC) marker ALDH1 and epithelial-mesenchymal transition marker (EMT) markers E cadherin, vimentin, Twist, and SNAI2 expression were evaluated in conjunction with the two optimal reference genes in 10 rectal cancers as part of validation." (PMID 33457124, 2020). "In our study, vimentin expression is abundant in rectal cancer stroma, although rectal cancer cells did not express vimentin." (PMID 37749564, 2023).
renal oncocytoma (3 papers, 2017 to 2023). "Vimentin may be another marker helping in the differential diagnosis between ESC-RCC and chromophobe RCC or renal oncocytoma." (PMID 35203531, 2022). "Vimentin is usually negative in chromophobe RCC and negative or only focally positive in renal oncocytoma (positivity of single cells, usually near to central scary area)." (PMID 35203531, 2022).
seminoma (3 papers, 2015 to 2025). A radiosensitive malignant germ cell tumor found in the testis (especially undescended), and extragonadal sites (anterior mediastinum and pineal gland). "Of them, 14-3-3γ, ezrin, filamin A, Parkinsonism-associated deglycase 7 (PARK7), vimentin and vinculin, were validated in CS I seminoma patient cohort." (PMID 34771736, 2021). "While 14-3-3γ, ezrin, filamin A, PARK7, vinculin and vimentin could be analysed in cohort of CS I seminoma patients using IHC to validate their clinical relevance, IHC evaluation in the case of caldesmon and 14-3-3β failed (data were non-homogenous and suboptimal)." (PMID 34771736, 2021). "Seminomas typically stain positively for placental alkaline phosphatase (PLAP), CD117/c-Kit, OCT3/4, SALL4, vimentin, and D2-40." (PMID 25705542, 2015).
serous carcinomas (3 papers, 2019 to 2023).
skin cancer (3 papers, 2012 to 2019). "We next examined the relationships between UBE3C, E-cadherin and vimentin expression and the clinicopathological features associated with skin cancer." (PMID 26894856, 2016). "In the present study, we analyzed the expression of UBE3C and two typical EMT markers, E-cadherin and vimentin, in skin cancer and normal skin tissues." (PMID 26894856, 2016). "We also assessed the protein expression of the epithelial marker E-cadherin and the mesenchymal marker vimentin in the same human skin cancer tissue microarrays." (PMID 26894856, 2016). "Our findings also highlight activation of TRIM16 nuclear translocation or degradation of vimentin and E2F1 as potential novel therapeutic strategies for the treatment of skin cancers." (PMID 22009481, 2012).
testicular cancer (3 papers, 2019 to 2024). A primary or metastatic malignant neoplasm that affects the testis. "Similar results have been recently reported in testicular cancer cells, where downregulation of PANX1 or its inhibition downregulated vimentin protein levels and upregulated E-cadherin protein levels, through signal-regulated kinase (ERK)." (PMID 31817827, 2019).
Type 1 diabetes (3 papers, 2021 to 2025). "Type 1 diabetes induced a significant upregulation in the mean fold change of relative mRNA expression of the renal cytoskeleton (stress indicators): desmin, vimentin, nestin, fibronectin-1, Coli-1, and α-SMA." (PMID 38044936, 2023).
upper tract urothelial carcinoma (3 papers, 2022 to 2023). "Additionally, survival analysis showed that lower VIM promoter methylation levels independently predicted for poor disease-specific survival in upper tract urothelial carcinoma (UTUC) patients." (PMID 36594099, 2023). "Interestingly, the upregulation and extension of vimentin was found in tumor islands of upper tract urothelial carcinoma infiltrated by natural killer cells." (PMID 36032170, 2022).
uveal melanoma (3 papers, 2014 to 2020). A melanoma derived from melanocytes of the uveal tract. "Proteomic analysis of uveal melanoma from patients with distant metastases has shown increased expression of vimentin and TIM, among other proteins, in comparison to patients without metastases." (PMID 24392146, 2014). "Moreover, we found that, in response to uveal melanoma, retinal pericytes increased levels of TGF-β1 and vimentin, both considered as CAF markers, and reduced NG2 levels." (PMID 32756477, 2020).
vitamin D deficiency (3 papers, 2014 to 2019). A nutritional condition produced by a deficiency of VITAMIN D in the diet, insufficient production of vitamin D in the skin, inadequate absorption of vitamin D from the diet, or abnormal conversion of vitamin D to its bioactive metabolites. "By contrast, vitamin D deficiency aggravated BLM-induced upregulation of vimentin and α-SMA in the lungs." (PMID 31775746, 2019). "Unexpectedly, vitamin D deficiency slightly upregulated the expression of pulmonary vimentin." (PMID 31775746, 2019). "Moreover, vitamin D deficiency aggravated BLM-induced upregulation of vimentin in the lungs." (PMID 31775746, 2019). "We previously demonstrated an increased expression of vimentin and α-SMA, both markers of cellular phenotypic alteration, in the renal cortex of rats under vitamin D deficiency euthanized 60 days after I/R injury." (PMID 30370270, 2018). "In addition, vitamin D deficiency may be involved in this cellular phenotypic alteration, since the animals from VDD+IRI groups presented a significant expression of vimentin and a slight increase of α-SMA expression when compared to IRI group." (PMID 25222475, 2014).
acute rheumatic fever (2 papers, 2018 to 2021). "Vimentin is mimickedby some bacterial proteins and anti-vimentin antibodies occur in autoimmunecardiac disease, as rheumatic fever." (PMID 29538505, 2018).
adrenocortical adenoma (2 papers, 2017 to 2018). "However, mesoderm-derived tissues such as the adrenal cortex normally express vimentin, while N-cadherin was reported to be downregulated in ACC compared to adrenocortical adenomas." (PMID 28881628, 2017).
Age-related cataract (2 papers, 2010). A type of cataract (opacification of the lens) that forms during the course of aging. "A study on expression of vimentin in lens epithelium of age-related cataract suggested that damage to the lens epithelial cells might initiate a decrease in vimentin expression leading to degradation of the lens cytoskeleton." (PMID 20689825, 2010).
Alexander disease (2 papers, 2015 to 2016). Alexander disease (AxD) is a rare neurodegenerative disorder of the astrocytes comprised of two clinical forms: AxD Type I and Type II manifesting with various degrees of macrocephaly, spasticity, ataxia and seizures and leading to psychomotor regression and death. "Astrocytic GFAP expression is associated with aging and AD; dominant GFAP mutations in Alexander disease cause protein aggregates that contain GFAP, vimentin, plectin, ubiquitin, and small chaperones such as α‐crystallin." (PMID 27448508, 2016). "Several of the most enriched proteins (plectin, glial fibrillar acidic protein, vimentin, Hsp 27, and ubiquitin) are known to form complex astrocytic inclusions, so-called Rosenthal fibers, in the neurodegenerative disorder Alexander disease." (PMID 24798087, 2015). "Interestingly, some of the BMAA-induced enriched proteins in the histopathologically altered area, such as plectin, GFAP, vimentin, Hsp 27, and ubiquitin, are known to form complex astrocytic inclusions, the so-called Rosenthal fibers, in the neurodegenerative disorder Alexander disease." (PMID 24798087, 2015).
allergic disease (2 papers, 2017 to 2021). An immune response that occurs following re-exposure to an innocuous antigen, and that requires the presence of existing antibodies against that antigen. "Among the identified allergenic-related proteins, VIM was found to be involved in the progression of allergic diseases via inflammasome and VIM-P38MAPK complex facilitates mast cell activation via FcεRI/CCR1 activation." (PMID 34394070, 2021).
angiomyolipoma (2 papers, 2012 to 2014). A neoplasm with perivascular epithelioid cell differentiation often associated with tuberous sclerosis. "In the present study, we investigated the role of tuberin/mTOR in regulating N-cadherin and vimentin as major fibrosis proteins involved in the progression and development of angiomyolipomas in TSC patients." (PMID 25149531, 2014). "Our data show that deficiency in tuberin in AML cells resulted in increased expression of vimentin and decreased expression of N-cadherin suggesting that tuberin is a potential molecule involved in the development of fibrosis in angiomyolipomas." (PMID 25149531, 2014). "Data in Figure 5Dd showed a strong staining of vimentin in vessel and smooth muscle cells as well as around the fat cells in kidney section of angiomyolipoma tissue." (PMID 25149531, 2014). "The presence of perivascular epithelioid cells (PEC) is often used to characterize angiomyolipomas since these cells show immunoreactivity for muscle markers (epithelial membrane antigen, keratin, vimentin, desmin, and actin) and HMB-45." (PMID 24555133, 2012).
angiomyxoma (2 papers, 2012 to 2024). A benign soft tissue neoplasm characterized by the presence of neoplastic spindle and stellate cells, and vascular proliferation in a myxoid stroma. "The histopathology of these three cases revealed invasive angiomyxoma, as confirmed by immunohistochemical staining, which demonstrated positive expression of desmin, vimentin, estrogen, and progesterone receptors." (PMID 38590660, 2024). "Superficial angiomyxomas are generally immunoreactive with vimentin and CD34, which was consistent with the present case." (PMID 22919399, 2012).
aortic stenosis (2 papers, 2017 to 2022). Aortic valve stenosis is a aortic valve disease caused by the incomplete opening of the aortic valve. "The analysis of the pericardial fluid proteome through a state-of-the-art MS instrument identified annexin A1, annexin A2, and vimentin as potential biomarkers of AF in severe aortic stenosis." (PMID 35207752, 2022). "In aortic valves from patients with aortic stenosis, galectin-3 co-localized with the α-smooth muscle cell markers actin and vimentin." (PMID 28471381, 2017).
Barrett esophagus (2 papers, 2018 to 2023). Esophageal lesion lined with columnar metaplastic epithelium which is flat or villiform. "More recently, a test called “EsoGuard”, which is based on the methylation analysis of CCNA1 and VIM genes in brush cells for the detection of Barrett’s esophagus, which is the precursor and a major risk factor for esophageal adenocarcinoma, has recently received CE-IVD certification." (PMID 37511475, 2023).
benign cystadenoma (2 papers, 2000 to 2023). "Lastly, two of the clusters of vimentin positive cells sequenced from those found in the benign cystadenoma case had CNA." (PMID 36781954, 2023). "Analysis of CTCs from the patient with benign cystadenoma revealed 9 clusters, with approximately 2 to16 cells per cluster of vimentin expressing cells." (PMID 36781954, 2023).
bone metastasis (2 papers, 2019 to 2022). Transfer of a neoplasm from its primary site to bones. "Low expression of VIM and RB1 (p = 0.020) but high ESR1 expression (p = 0.020) was identified in CTCs’ patients who had bone metastasis." (PMID 31817194, 2019).
cardiac hypertrophy (2 papers, 2021 to 2022). "As we cannot demonstrate a causal relationship between DHT and cardiac hypertrophy and/or fibrosis, we might, however, hypothesize a DHT-mediated increase in moesin and vimentin expression, which in turn might be associated with LVH and fibrosis." (PMID 36206048, 2022). "In accordance with these findings from cell culture and animal studies, we can describe the association between higher serum levels of DHT, increased moesin and vimentin expression levels, and higher degree of cardiac hypertrophy and fibrosis in patients with severe AS." (PMID 36206048, 2022).
cerebral amyloid angiopathy (2 papers, 2019 to 2021). "ANK1 binds to the erythrocyte membrane protein band 4.2 (EPB42, present in this module) to vimentin which is implicated in neuroinflammation and in cerebral amyloid angiopathy, which is one of the major causes of ICH." (PMID 30836997, 2019).
Chagas disease (2 papers, 2018 to 2021). A parasitic infection caused by Trypanosoma cruzi. "Of the seven potential biomarkers that were screened, vimentin, 8-OHdG, copeptin, and endostatin exhibited excellent performance in distinguishing the clinical severity of Chagas disease." (PMID 34479416, 2021). "In this work we studied vimentindistribution on LLC-MK2 cells infected with T. cruzi and anti-vimentinantibodies in sera from several clinical pictures of Chagas' disease orAmerican Trypanosomiasis, in order to elucidate any vimentin involvement inthe humoral response of this pathology." (PMID 29538505, 2018).
chronic myelogenous leukemia (2 papers, 2020 to 2024). "HAND2‐AS1 restoration resulted in reduced N‐cadherin, vimentin, MMP‐2 and MMP‐9 expression, which was consistent with a former study in which HAND2‐AS1 reduced MMP‐2 and MMP‐9 expressions in chronic myeloid leukaemia." (PMID 32314545, 2020).
cobalamin deficiency (2 papers, 2020 to 2022). "Herein, we found that vimentin expression in astrocytes upon cobalamin deficiency was 1.6-fold higher than that of the control group, as assessed by Western blotting." (PMID 33050187, 2020).
congenital cataracts (2 papers, 2017 to 2022). "The mutation of VIM (p.E151K) is associated with inherited congenital cataracts." (PMID 28450710, 2017). "Vimentin (VIM), the major intermediary filament constituent, was associated with neuritogenesis, cell signaling, attachment, and migration, causing congenital cataracts." (PMID 35571016, 2022).
coronary atherosclerosis (2 papers, 2019 to 2021). Atherosclerosis of the coronary vasculature. "In patients with coronary atherosclerosis, the proteomic profile of stable atherosclerotic plaques of the coronary arteries showed a significant increase in the content of proteins: actin, tropomyosin, vimentin, keratin, tubulin and microfibrils of associated glycoprotein 4 (MAGP-4)." (PMID 34948066, 2021).
desmoplastic small round cell tumor (2 papers, 2021 to 2022). Desmoplastic small round cell tumor (DSRCT) is an aggressive soft tissue cancer that typically arises in serous lined surfaces of the abdominal or pelvic peritoneum, and spreads to the omentum, lymph nodes and hematogenously disseminates especially to the liver. "Desmoplastic small round-cell tumors (DSRCTs) possess a distinctive, diagnostically significant immunophenotype, showing coexpression of epithelial (keratin), mesenchymal (desmin, vimentin), and neural (NSE) markers." (PMID 35372059, 2022). "Osteosarcoma and desmoplastic small round cell tumors (DSRCT) have been documented to express both epithelial and mesenchymal markers, such as keratin, cadherins, desmin, and vimentin." (PMID 34063272, 2021).
dilated cardiomyopathy (2 papers, 2014 to 2026). Cardiomyopathy which is characterized by dilation and contractile dysfunction of the left and right ventricles. "Immunohistochemical analysis showed abnormal expression patterns of desmin, vimentin, and connexin 43, similar to those previously reported in humans and dogs with dilated cardiomyopathy." (PMID 42110576, 2026).
embryonal rhabdomyosarcoma (2 papers, 2017 to 2019). A poorly circumscribed morphologic variant of rhabdomyosarcoma. "Immunohistochemical stains were positive for vimentin, CD99, myogenin, and MyoD1 consistent with a diagnosis of embryonal rhabdomyosarcoma, botryoid subtype." (PMID 29375950, 2017).
enthesitis (2 papers, 2013 to 2020). Inflammation at the site of insertion of ligaments, tendons, and other fibrous structures into bone. "The enthesitis-related and psoriatic arthritis groups were rather small, with larger populations needed in future studies to confirm the significance of citrullinated type II collagen and vimentin autoantibodies in these subtypes." (PMID 23987731, 2013).
Epstein-Barr virus infection (2 papers, 2017 to 2022). An infection that is caused by Epstein-Barr virus. "Besides, Epstein-Barr virus infection of B cell line induces dramatic increase in VIM mRNA and protein expression, further implying a possible role of VIM in infectious diseases." (PMID 35465354, 2022). "Additionally, the pathway ‘Epstein-Barr virus infection’ was simultaneously enriched, in which several genes including BCL2, CD39, HSP70, HDAC45, IL10, IL10R and vimentin were up-regulated, together with some down-regulated genes such as CD38, NUP214, RBP-Jκ, CycA, TAK1 and TBK1." (PMID 28912500, 2017).
experimental autoimmune encephalomyelitis (2 papers, 2011 to 2022). An autoimmune demyelinating disease of the central nervous system that is produced experimentally in animals by the injection of homogenized brain or spinal cord in Freund's adjuvant. "Enhanced vimentin immunoreactivity was found in the spinal cord of rats with experimental autoimmune encephalomyelitis." (PMID 21297967, 2011).
extraskeletal osteosarcoma (2 papers, 2021 to 2024). "Histopathology and immunohistochemical analysis revealed positive reactions for Vimentin, Runx-2 and ki-67, leading to a diagnosis of extraskeletal osteosarcoma (ESOS)." (PMID 39399861, 2024). "The tumor cells exhibited heterogeneous protein expression, including a positive expression of vimentin, cytokeratin, RANKL, CRLR, SOX9, and collagen 2, and was diagnosed as extraskeletal osteosarcoma." (PMID 34941834, 2021).
fibroepithelial tumours (2 papers, 2008 to 2023). "Tse described the immunohistochemical profile of the infrequent MSGCs in phyllodes tumours, commenting that both the MSGCs and stromal cells expressed vimentin strongly but not desmin; and in some but not all fibroepithelial tumours, both MSGCs and stromal cells expressed actin weakly." (PMID 18673528, 2008).
follicular thyroid carcinoma (2 papers, 2016 to 2018). "In follicular thyroid carcinomas, the rhabdoid inclusions are vimentin-positive but lack immunoreactivity for cytokeratins, thyroglobulin, smooth-muscle actin, and desmin." (PMID 29938394, 2018). "However, key epithelial-to-mesenchymal transition (EMT) markers including E-cadherin and vimentin as well as Slug were not affected by cyclopamine and GANT61 in either SW1736 or WRO82, a well differentiated follicular thyroid carcinoma cell line." (PMID 26859575, 2016).